PRR33 (proline rich 33)
Synonyms: C11orf89; LOC728008
Gene: Protein-coding gene on chromosome 11 (1,888,078 to 1,891,895, reverse strand). Ensembl gene ENSG00000283787.
Homologues: Orthologues: chimpanzee PRR33 (98% identical), macaque PRR33 (87% identical), dog PRR33 (59% identical), mouse Prr33 (59% identical), rat Prr33 (58% identical), pig PRR33 (53% identical).
Diseases named in the same sentence as PRR33 in open-access papers:
PRR33 is named in the same sentence as 1 disease in open-access papers, as found by Europe PMC text mining. Sharing a sentence is not in itself a finding about the gene and the disease. The quoted sentences say what the papers report.
breast carcinoma (1 paper, 2023). "Six of these genes (MRPS30, SETD9, ADGRV1, ZNF703, PRR33, and PSG4) showed different directions of association with breast cancer in epithelial vs. stromal (nonepithelial) cells." (PMID 36690614, 2023).